ZNF415 (zinc finger protein 415)
Description:
Involved in transcriptional regulation. Transcriptional activity differed among the various isoforms.
Synonyms: Pact; ZfLp
Tractability: PROTAC: ubiquitination databases record sites on it.
Gene: Protein-coding gene on chromosome 19 (53,107,879 to 53,133,077, reverse strand). Ensembl gene ENSG00000170954.
Subcellular location: Nucleus; Cytoplasm
Subcellular location (Human Protein Atlas): Microtubules; Nucleoli fibrillar center
Pathways (Reactome):
Gene expression (Transcription): Generic Transcription Pathway
Gene Ontology:
Molecular function: protein binding; DNA-binding transcription factor activity, RNA polymerase II-specific; RNA polymerase II cis-regulatory region sequence-specific DNA binding; sequence-specific double-stranded DNA binding
Biological process: regulation of transcription by RNA polymerase II
Cellular component: nucleus; cytoplasm
Genetic constraint (gnomAD): Loss-of-function variants: 5 observed, 8.11 expected, observed/expected ratio (o/e) 0.62, 90% interval 0.32 to 1.29. That is too few expected variants to judge how well the gene tolerates losing a copy. Missense variants: 628 observed, 696.98 expected, observed/expected ratio (o/e) 0.9, 90% interval 0.84 to 0.96. Synonymous variants: 207 observed, 235.73 expected, observed/expected ratio (o/e) 0.88, 90% interval 0.78 to 0.99.
Homologues: Orthologues: chimpanzee ZNF415 (98% identical), macaque ZNF415 (94% identical), rabbit ZNF415 (50% identical). Paralogues in human: ZNF841 (52% identical), ZNF836 (51% identical), ZNF528 (46% identical), ZNF616 (46% identical), ZNF28 (45% identical), ZNF546 (44% identical), ZNF534 (43% identical), ZNF226 (43% identical), ZNF658 (43% identical), ZNF568 (43% identical), ZNF540 (43% identical), ZNF571 (43% identical), and 164 more.
Diseases named in the same sentence as ZNF415 in open-access papers:
ZNF415 is named in the same sentence as 9 diseases in open-access papers, as found by Europe PMC text mining. Sharing a sentence is not in itself a finding about the gene and the disease. The quoted sentences say what the papers report.
sarcopenia (4 papers, 2022 to 2024). Progressive decline in muscle mass due to aging which results in decreased functional capacity of muscles. "In this research, six genetic biomarkers closely associated with sarcopenia, including ARHGAP36, FAM171A1, GPCPD1, MT1X, ZNF415, and RXRG, were identified by WGNCA and LASSO analysis, which were used to future diagnose and screen for sarcopenia." (PMID 36147639, 2022). "Additionally, in patients with sarcopenia, MT1X and ARHGAP36 were upregulated, whereas FAM171A1, GPCPD1, ZNF415 and RXRG, were downregulated, demonstrating high diagnostic accuracy for sarcopenia and potential as predictive markers for screening." (PMID 38337720, 2024). "Finally, six hub genes with AUC exceeding 0.9, including GPCPD1, MT1X, ARHGAP36, FAM171A1, ZNF415, and RXRG, were defined as diagnostic biomarkers of sarcopenia." (PMID 36147639, 2022). "We found the AUC values of GPCPD1, MT1X, ARHGAP36, FAM171A1, ZNF415, and RXRG on the validation dataset were 0.928, 0.75, 0.978, 0.961, 0.811, and 0.906, indicating that the six biomarkers had high diagnostic accuracy for sarcopenia." (PMID 36147639, 2022). "Moreover, six hub genes with AUC exceeding 0.9, including ARHGAP36, FAM171A1, GPCPD1, MT1X, ZNF415, and RXRG, were confirmed as diagnostic biomarkers for sarcopenia." (PMID 36147639, 2022). "Compared to normal samples, the expression levels of both MT1X and ARHGAP36 were upregulated in sarcopenia samples, while GPCPD1, FAM171A1, ZNF415, and RXRG showed lower expression in sarcopenia samples." (PMID 36147639, 2022).
psoriasis (2 papers, 2022 to 2025). An autoimmune condition characterized by red, well-delineated plaques with silvery scales that are usually on the extensor surfaces and scalp. "Our work proposed that STFs (PPARG, ZFPM2, ZNF415, HLX, and ANHX) mediate the initiation of chronic inflammation and metabolic disorders that increase the risk of developing AD in the psoriasis population." (PMID 35669784, 2022). "In this study, the expression levels of ZNF415 isoforms need to be further investigated in psoriasis and AD experimentally." (PMID 35669784, 2022). "We identified 5 STFs (PPARG, ZFPM2, ZNF415, HLX, and ANHX) in common DEGs and investigated their potential roles in psoriasis and AD." (PMID 35669784, 2022). "Among these, four genes, PPARG, ZFPM2, ZNF415, and HLX, were down-regulated and ANHX upregulated in psoriasis and AD." (PMID 35669784, 2022). "ZNF384 is a potential therapeutic target for psoriasis and AD by regulating PPARG, ZNF415, HLX, and ANHX." (PMID 35669784, 2022). "Additionally, ZNF384 was identified as the key transcription factor that modulates the expression of PPARG, ZNF415, HLX, and ANHX, pointing to its potential as a therapeutic target for psoriasis and AD." (PMID 40343299, 2025). "PPARG, ZFPM2, ZNF415, and HLX were down-regulated in psoriasis and AD, while ANHX was up-regulated." (PMID 40343299, 2025). "The STFs (PPARG, ZFPM2, ZNF415, HLX, and ANHX) may increase the morbidity rate of AD in psoriasis by initiating a positive feedback loop of excessive inflammation and metabolic disorders." (PMID 35669784, 2022).
asthma (1 paper, 2024). "In addition, the ZNF415 rs1054485-G allele has been associated with significantly higher eosinophil counts and asthma." (PMID 39125709, 2024).
metabolic syndrome (1 paper, 2022). A cluster of metabolic risk factors for CARDIOVASCULAR DISEASES and TYPE 2 DIABETES MELLITUS. "ZNF384 is the potential transcription factor that may modulate STFs PPARG, ZNF415, HLX, and ANHX, thus subsequently triggering hyperinflammatory states and metabolic syndromes." (PMID 35669784, 2022).
tumor (2 papers, 2020 to 2021). "Conversely, eRNAs chr19.53635063.53635358 and chrX.11360130.11360328 were found to be located near the tumor-suppressor genes ZNF415 and ARHGAP6." (PMID 34439379, 2021). "Similarly, we found that eRNAs chr19.53635063.53635358 and chrX.11360130.11360328 were downregulated and located near ZNF415 and ARHGAP6, which have been identified as tumor-suppressor genes." (PMID 34439379, 2021).
cancer (1 paper, 2015). A tumor composed of atypical neoplastic, often pleomorphic cells that invade other tissues. "Seven genes are hypermethylated in ten cancer sites: six encoding zinc finger transcription factors (ZNF135, ZNF354C, ZNF415, ZNF542, ZNF671, ZSCAN18) and one encoding a transmembrane protein (TMEM25)." (PMID 25631659, 2015).
ZNF415 also shares sentences with these, for which no sentence is quoted: metabolic disorders (1 paper); pancreatic adenocarcinoma (1); type 2 diabetes (1).